IL21R (interleukin 21 receptor)
Diseases named in the same sentence as IL21R in open-access papers (continued):
Sharing a sentence is not in itself a finding about the gene and the disease.
infection (continued). "Consistent with our findings that IFN-γ, but not IFN-α, was the dominant interferon expressed in the colon after infection with C. rodentium, significantly lower concentrations of IFN-α than IFN-γ were detected in the colon of both infected WT and Il21r-/- mice." (PMID 30818341, 2019). "We first looked 4 weeks after infection in MBMC or intact WT and IL-21R−/− mice." (PMID 27819295, 2016). "A time course showed that after low dose aerosol M. tuberculosis infection, WT and IL-21R−/− mice had a similar lung bacillary burden at four weeks (peak immune response); however, by 16 weeks (chronic phase of infection), WT mice had lower lung CFU compared to IL-21R−/− mice." (PMID 27819295, 2016). "Although the defect in reactivation in IL-21R-/- mice is linked to the reduced frequency of infected plasma cells, what impact this has on MHV68 infection is not clear." (PMID 25875847, 2015). "Both infected and uninfected germinal center B cell populations in IL-21R-/- mice are skewed towards the non-proliferating centrocyte pool, resulting in reduced proliferation of infected germinal center B cells and reduced infection." (PMID 25875847, 2015). "Because infected Il21-/- and Il21r-/- mice cannot make P. chabaudi-specific IgG responses, and in particular MBC responses, we reasoned that lack of IL-21 signaling would render these mice unable to control a re-infection." (PMID 25763578, 2015). "However, these IL-21R levels were comparatively high in MABS infection due to suppression in MAC infection rather than an increase associated with MABS." (PMID 36439147, 2022). "Furthermore, mucosal CD4+ T cells expressed higher levels of transcripts for IL-21R as compared with other immune and non-immune cells after infection with C. rodentium." (PMID 30818341, 2019). "Interestingly, the colonic intestinal epithelial cells (IECs) expressed neither detectable transcripts for IL-21 nor mRNA for IL-21R following infection." (PMID 30818341, 2019). "We found that an intact IL-21/IL-21R axis was required for resistance against and clearance of enteric infection with this pathogen and that activated CD4+ T cells were the exclusive expressors of IL-21 following infection with C. rodentium in the distal colon." (PMID 30818341, 2019). "Notably, although there is a statistically significant defect in generating germinal center B cells in IL-21R-/- mice, it is much smaller than the defect in establishment of MHV68 infection, indicating that the lack IL-21 signaling has a greater effect on infected B cells than on uninfected B cells." (PMID 25875847, 2015). "In order to examine this hypothesis, we analyzed IL-21R expression on B cell subsets at 3 dpi in our culture system with or without IL-21 supplementation to determine whether KSHV and/or IL-21 can modulate the response to IL-21 during infection by modifying expression of IL-21R." (PMID 36569889, 2022). "Although there was a statistically significant decrease in the overall GC population in IL-21R-/- mice (<2-fold), it was not as severe as the defect in overall MHV68 infection (~10-fold at days 16–20 post-infection)." (PMID 25875847, 2015). "Together with the Treg cell-intrinsic negative IL-21R−/− signaling observed in WT:IL-21R−/− mixed BM chimeras, these data suggest that IL-21 restricted the virus-driven Treg cell expansion in LCMV-DOC infection independently of IL-6 signaling." (PMID 23696736, 2013). "In the present study, mRNA coding for cytokines and cytokine receptors involved in the JAK-STAT pathway, including IL19, IL20, IL21R, and IL22RA2, were highly expressed in lower trachea during host-adapted swH1N1 infection compared to non-adapted huH1N1 infection." (PMID 39247193, 2024).
infection (continued). "Collectively, these findings suggested that IFN-γ is the predominant interferon produced in the colon in response to C. rodentium and that the lack of an intact IL-21/IL-21R signaling axis does not negatively affect the IFN-γ expression and production in response to infection in Il21r-/- mice." (PMID 30818341, 2019).
cancer (16 papers, 2010 to 2025). A tumor composed of atypical neoplastic, often pleomorphic cells that invade other tissues. "IL-21/IL-21R signaling plays critical role in immune responses and has been implicated in the regulation of inflammation in various acute and chronic inflammatory diseases, such as cancer." (PMID 38720319, 2024). "Furthermore, cytokines Ccl2, Ccl4, Ccl7, Ccl22, and Il21r, which associated with an M2-like, pro-cancer macrophage phenotype, were found to be consistently downregulated at both days 5 and 10 post-challenge." (PMID 37066426, 2024). "Taken together, these observations in human and mouse HCC samples suggest a potential cancer-promoting role of IL-21R in MASH-driven HCC." (PMID 38720319, 2024). "In conclusion, our findings explore the cancer-promoting role of IL-21R in MASH-driven hepatocarcinogenesis and elucidate the mechanism by which IL-21R activates IgA via the IL-21R-STAT-1-c-Jun/c-Fos-IgA regulatory axis." (PMID 38720319, 2024). "The results indicated that seven risk genes (SERPINE1, LAMC2, MYLK, IL21R, KRT81, MAMDC2, and PAEP) of the signature were differentially expressed in the cancer tissues compared to the normal tissues." (PMID 37636564, 2023). "Moreover, miR-125a-3p participates in the development of cancer by mediating downstream factors, such as FOXM1and IL-21R." (PMID 38403680, 2024). "The results revealed that IL-21R played a cancer-promoting role by activating the IL-21R-STAT1-c-Jun/c-Fos regulatory axis, resulting in the production of immunosuppressive IgA+ B cells, and thus attenuated CTL activation in the tumorigenesis of MASH-driven HCC." (PMID 38720319, 2024). "IL-21R plays a cancer-promoting role by inducing IgA+ B cells in MASH-driven hepatocarcinogenesis." (PMID 38720319, 2024). "Targeting IL-21R signaling represents a potential therapeutic strategy for cancer therapy." (PMID 38720319, 2024). "Thus, targeting IL-21R signaling represents a potential therapeutic strategy for cancer therapy." (PMID 38720319, 2024). "Partially because the methods are optimized for different cancer types, the overlap between genes used in the TMEPRE model and genes used in the TIDE model is small (IL21R, GZMA)." (PMID 34594218, 2021). "The role of IL-21/IL-21R in cancer development remains obscure and has not been extensively investigated in faithful in vivo models." (PMID 38720319, 2024). "From the differential genes involved in these pathways, we identified several gene clusters uniquely upregulated in the CAFWPOI 4-5 type; neuronal development and function-related (RELN, MYH10, CACNB4, OXTR, CAV3, CHRM2) and inflammation and cancer-related (RELN, IL21R, EDNRB, CAV3, OXTR)." (PMID 36045118, 2022). "However, the role of IL-21/IL-21R in cancer development remains controversial and has not been extensively investigated in faithful in vivo models." (PMID 38720319, 2024).
renal disease (2 papers, 2011). "Treatment with IL-21R.Fc reduced renal disease, skin lesions and circulating auto-antibodies in these MRL-Faslpr mice." (PMID 21959034, 2011).
bacterial infection (1 paper, 2016). "A bacterial infection can elicit IgM memory B-cells which requires T cell- dependent and IL-21R signaling." (PMID 28003017, 2016).
IL21R also shares sentences with these, for which no sentence is quoted: Crohn disease (4 papers); colon carcinoma (3); multiple sclerosis (3); cholangitis (2); eosinophilia (2); gastrointestinal infections (2); acute myeloid leukemia (1); adenoma (1); Allergy (1); bare lymphocyte syndrome (1); benign prostatic hyperplasia (1); benign tumor (1); breast tumours (1); cerebral artery occlusion (1); chlamydia infection (1); chronic hepatitis C (1); congenital neutropenia (1); cutaneous leishmaniasis (1); eczema (1); endocrinopathies (1); follicular lymphoma (1); glioma (1); Hepatitis (1); HIV-1 infection (1); immunodeficiency syndrome (1); infectious colitis (1); infectious disease (1); inflammation (1); Insulin resistance (1); intestinal inflammation (1).
A further 21 diseases each share a sentence with IL21R in 1 paper.